CHI3L1 (chitinase 3 like 1)
Diseases named in the same sentence as CHI3L1 in open-access papers (continued):
Sharing a sentence is not in itself a finding about the gene and the disease.
tumor (339 papers, 1999 to 2026). "LC_cells3, marked by the expression of CHI3L1, constitutes the major tumor cell subtype associated with LC-BoM." (PMID 41362730, 2026). "In a mouse model of AOM/DSS-induced colitis-associated cancer, CHI3L1 expression is significantly upregulated in intestinal epithelial cells, contributing to tumor initiation and progression." (PMID 40643503, 2025). "The incidence of B symptoms (fever, night sweats, and weight loss) also increased significantly with higher CHI3L1 levels, further reflecting heightened tumor activity (P > 0.05)." (PMID 40260255, 2025). "The overexpression of CHI3L1 in NPC cells is linked with tumour-associated inflammation and proliferation, and for this cancer, like several others, CHI3L1 is being considered not only as a diagnostic marker, but also as a potential therapeutic target." (PMID 40769579, 2025). "YKL-40, also known as chitinase-3-like protein 1 (CHI3L1), is an inflammatory biomarker produced locally at inflammation sites by cells such as tumour-associated macrophages and cancer cells." (PMID 40188292, 2025). "A representative CLP is chitinase 3-like 1 (CHI3L1, also known as YKL-40 in humans and Brp-39 in mice), a multifunctional glycoprotein implicated in inflammation, tissue repair, fibrosis, and tumor development." (PMID 40643503, 2025). "In frozen patient samples, CHI3L1 and osteopontin immunostainings were significantly more intense in tumor samples than in control brainstem, and they were associated to SOX2+ cancer cells." (PMID 40703808, 2025). "Secreted by tumor-associated astrocytes, chitinase 3-like 1 (CHI3L1) binds to IL-13 receptor alpha 2 (IL-13Rα2) on the tumor cell surface." (PMID 40345526, 2025). "Elevated serum CHI3L1 levels are positively associated with tumor progression, metastasis, recurrence rate, and reduced overall survival." (PMID 40643503, 2025). "In inflammation-associated cancers, CHI3L1 expression in tumor tissues is consistently associated with increased tumor aggressiveness, higher histological grade, advanced clinical stage, and poorer prognosis." (PMID 40643503, 2025). "Although CHI3L1 has been implicated in inflammation, fibrosis, and tumor progression in higher mammals, including humans, its regulatory mechanisms, functional roles, and interactions at the cellular and tissue levels remain incompletely understood." (PMID 40643503, 2025). "CHI3L1 also influences the differentiation of macrophages towards an M2-like phenotype, associated with immunosuppression and tumor-promoting activity." (PMID 39827337, 2025). "In vitro assays demonstrate that Gr1+ cells from early metastatic lungs support tumor cell survival, migration, and proliferation, which is linked to chitinase-3-like protein 1 (CHI3L1) signaling." (PMID 40269509, 2025). "It has been observed that Chi3l1 is strongly associated with greater tumor aggressiveness, worse outcomes, and shorter survival rates." (PMID 38291404, 2024). "In the context of chronic inflammation, CHI3L1 plays a crucial role in fostering tumor-associated inflammation and shaping the tumor microenvironment." (PMID 38667293, 2024). "High CHI3L1(YKL40) levels are often associated with aggressive tumor behavior, cancer metastasis, and poor prognosis." (PMID 38543093, 2024). "Further investigations revealed that CHI3L1 plays a role in reshaping the tumor microenvironment by promoting angiogenesis and inducing the transformation of tumor-associated macrophages (TAMs) and neutrophils (TANs)." (PMID 39000203, 2024). "In solid tumors, CHI3L1 is mainly produced by cancerous and tumor-associated immune cells that infiltrate the vicinity of the tumor tissue." (PMID 39068486, 2024). "The analysis revealed that tumor grade, age, CHI3L1, and ORGI were identified as risk factors with HR 4.18, 1.022, 3.346, and 3.222, respectively, all with p-values of less than 0.001." (PMID 39000203, 2024).
tumor (continued). "For example, in glioblastoma, upregulation of cancer-intrinsic CHI3L1 signaling regulates the immunosuppressive microenvironment by reprogramming tumor-associated macrophages, leading to tumor progression." (PMID 38962736, 2024). "CHI3L1 recruits and polarizes tumor-associated macrophages (TAMs) toward an M2-like phenotype, suppressing antitumor immune responses and promoting angiogenesis." (PMID 38177294, 2024). "As a result, reduction of CHI3L1 levels in the primary tumor upon chitin treatment would be intricately linked to reduced Stat3 phosphorylation." (PMID 38605414, 2024). "This review focuses on recently significant reported molecular mechanisms of CHI3L1 and inflammation-associated tumours, which provides new ideas to explore the development of inflammation-associated tumours." (PMID 39068486, 2024). "We found that CHI3L1 was significantly associated with age (P < 0.001), sex (P = 0.002), tumor size (P < 0.001), the HCC biomarker DCP (P < 0.001), and NLR (P = 0.003)." (PMID 39513118, 2024). "Other studies also reported an association between high expression levels of CHI3L1 and low survival, poor prognosis or advanced tumor stage in patients with PDAC." (PMID 39225813, 2024). "The list includes several markers indicative of a decreased mesenchymal phenotype, for example expression of CHI3L1 (encoding YKL-40) was downregulated over fivefold in 3 of 4 G⍺12 KD tumor samples." (PMID 38104152, 2023). "In CRC tumor tissue, CHI3L1 is associated with the expression of MMP-8, IL17A, and PD-L1, thereby influencing the tumor microenvironment." (PMID 38003338, 2023). "The close relationship between tumor-associated macrophages (TAMs) and CHI3L1 has been demonstrated in many diseases, especially during inflammation." (PMID 38003338, 2023). "Aberrant CHI3L1 expression is also reportedly associated with tumor migration and metastasis, as well as contributions to immune escape, playing important roles in tumor progression." (PMID 38003338, 2023). "CHI3L1 is also specifically upregulated in cancer-associated fibroblasts (CAFs), and CAF-derived CHI3L1 appears to be unique in that it can reprogram TAMs into an M2-like phenotype, which is associated with tumor progression." (PMID 38003338, 2023). "that CHI3L1 reprograms tumor-associated macrophages, which alters an immune-suppressive milieu (TAMs)." (PMID 37091145, 2023). "Association study showed that plasma CHI3L1 levels correlated with tumor tissue Rab37 expression (P = 0.008), validating for the first time that Rab37 mediates CHI3L1 secretion in PDAC clinical model." (PMID 34987649, 2022). "CHI3L1 is involved in cell proliferation and differentiation and is possibly associated with tumor transformation." (PMID 35454784, 2022). "More recently, a positive correlation between tumour-associated CHI3L1 and IL-8 protein levels with tumour growth has also been reported." (PMID 35203465, 2022). "We found that a significantly higher CHI3L1 expression level was associated with T3&T4 tumor as compared to T1 tumor (T1 vs T3&T4)." (PMID 34612767, 2021). "To find any association of IFN signaling in tumor cells with mesenchymal phenotypes, we chose five well-established signature genes of the mesenchymal phenotype: CHI3L1, CD44, SERPINE1, TNC, and TIMP1." (PMID 34771447, 2021). "Chitinase 3-like 1 (CHI3L1) is an enzymatically inactive mammalian chitinase that is associated with tumor inflammation." (PMID 33920100, 2021). "CHI3L1 signaling plays a critical role in cancer cell growth, proliferation, invasion, metastasis, angiogenesis, activation of tumor-associated macrophages, and Th2 polarization of CD4+ T cells." (PMID 32929074, 2020). "In contrast to tumor cells, tumor-associated astrocytes revealed a stable expression of CHI3L1 across all patients." (PMID 31561550, 2019).
tumor (continued). "Unexpectedly, our results showed that the CHI3L1 expression is mainly linked to a specific cluster of tumor cells and strongly varies between individual patients." (PMID 31561550, 2019). "We found Chitinase 3-like 1 (CHI3L1) to be the top up-regulated gene in tumor-associated astrocytes." (PMID 31561550, 2019). "In the reactive astrocytes from the tumor we identified an increased expression of immune associated genes such as CHI3L1, HLA-DRA, CD274, HLA-DRB3, CD37, as well as genes that contributed to proliferation (MKI67, ANXA2) and complement components (C1S, C1R)." (PMID 31186414, 2019). "In this work, we identified a strong release of CHI3L1 caused by tumor-astrocytic crosstalk in tumor specimens as well as in cell culture models." (PMID 31561550, 2019). "We then aimed to investigate the extent to which CHI3L1 release from TAA is linked to effects that were observed in co-cultured tumor cells." (PMID 31561550, 2019). "Correlation analysis revealed that high expression of CHI3L1 in GC tissues was significantly associated with a more aggressive tumor phenotype." (PMID 30165890, 2018). "Correlation of our in vitro finding with TCGA data suggests an in vivo association between NF1 status and tumor production of CHI3L1 and ENG, supporting an association between NF1 and mesenchymal identity in human GBM samples." (PMID 29643433, 2018). "YKL-40, which is encoded by the CHI3L1 gene, is produced by tumor cells, inflammatory cells, and stem cells." (PMID 29467925, 2018). "Chi3l1-deficient Th1 cells show increased expression of anti-tumor immunity genes and decreased Th1 negative regulators." (PMID 29403003, 2018). "In conclusion, dissemination of SCLC seems to be linked to conversion of regular tumor cells to highly invasive CHI3L1-positive CTCs, which are protected by immune system suppression." (PMID 26425658, 2015). "In multivariate Cox regression analysis, we found that high CHI3L1 expression, advanced stage, and residual tumor size > 1 cm after debulking surgery were independent risk factors for recurrence and death." (PMID 26452028, 2015). "Genotype distributions of the single nucleotide polymorphisms of the chitinase 3-like 1 gene in patients with neoplasia of the uterine cervix and normal controls." (PMID 25203433, 2014). "Under physiological conditions, CHI3L1 is minimally expressed, but its expression is inducible under conditions associated with environmental stress, inflammation, tissue injury, fibrosis, and tumor progression." (PMID 40643503, 2025). "Future studies should aim at validating GPNMB and CHI3L1 not only as markers of OCSC but also as causal players in OCSC-driven tumor progression and as putative targets in the context of tumor-eradicating strategies based on the elimination of the cancer stem cell subpopulation." (PMID 40204276, 2025). "In addition, serum CHI3L1 expression was significantly associated with age, sex, tumor size, DCP, and NLR." (PMID 39513118, 2024). "Therefore, delving into the interaction mechanism between CHI3L1 and other inflammatory factors can benefit our understanding of the mechanisms underlying inflammation response and tumor development." (PMID 39068486, 2024). "However, the mechanisms underlying how CHI3L1 drives NF-κB activation within tumor cells still warrant further investigation." (PMID 36276655, 2022). "In addition, our clinical IF-IHC results showed that intratumoral CHI3L1+ expression was associated with cancer progression in terms of tumor staging." (PMID 34987649, 2022).
tumor (continued). "Due to the limited number of samples in our previous data set, we purified astrocytes from an independent cohort (ctr n = 8, TAA n = 9) and validated the CHI3L1 expression by RT-qPCR, which confirmed a significant increase of CHI3L1 expression in tumor-associated astrocytes." (PMID 31561550, 2019). "Here, we report that CHI3L1 release is driven by tumor-associated reactive transformed astrocytes." (PMID 31561550, 2019). "Notably, the increased serum CHI3L1 levels were associated with invasion depth, lymph node status, and tumor staging." (PMID 30165890, 2018). "Moreover, little is known regarding the underlying mechanisms and key downstream targets of CHI3L1 in tumor metastasis." (PMID 30165890, 2018). "Furthermore, based on the Pearson correlation analysis, CHI3L1 stool level versus tumor multiplicity/size showed positive association in AOM/DSS-treated WT mice." (PMID 26431492, 2015). "This is tightly associated with strong tumor cell expression of CHI3L1 in the lung." (PMID 23613996, 2013). "CHI3L1 expression was found in different cancer cells, tumor-associated macrophages and inflammatory cells and is involved in cell proliferation, differentiation, protection from apoptosis, angiogenesis, and invasiveness via remodeling of the extracellular matrix." (PMID 23675241, 2011). "Interestingly, CHI3L1 overexpression in the murine model was associated with increased expression and activation of anti-tumor T-cell-related genes, suggesting that CHI3L1-targeted therapy might synergize with immune checkpoint inhibitors." (PMID 40643503, 2025). "However, the diagnostic specificity of CHI3L1 remains limited in several tumor types." (PMID 40643503, 2025). "Exerting a similar pro-tumor activity on iNKT cells, Porphyromonas gingivalis (Pg), an opportunistic oral pathogen previously associated with different inflammatory diseases and cancers, hampers the iNKT cell lytic machinery through increased expression of chitinase 3-like-1 protein (CHI3L1)." (PMID 40422223, 2025). "Chitin significantly reduced primary tumor progression in the 4T1-based model by decreasing the high production of CLPs that originate from tumor-associated neutrophils (TANs) and Stat3 signaling, prominently affecting the CHI3L1 and CHI3L3 primary tumor levels." (PMID 38605414, 2024). "Notably, CHI3L1 has been shown to drive the polarization of macrophages towards the M2 phenotype, commonly referred to as TAMs (tumor-associated macrophages), within the tumor microenvironment." (PMID 38667293, 2024). "GSEA results suggest that high CHI3L1 expression is associated with biological processes involved in cytokine production (IL-2 and IL-6), mTORC1 and complement signaling, interferon-γ response, and inflammatory response, leading to an immunosuppressive effect in the tumor microenvironment." (PMID 37185706, 2023). "Findings in synergistic mouse models confirm that CHI3L1 promotes tumor progression and immunosuppression even in immunocompetent settings, parallelling xenograft observations." (PMID 40643503, 2025). "In particular, in cancer-related inflammatory responses, CHI3L1 promotes tumor cell proliferation, migration, and immune evasion by binding to specific receptors (e.g., IL-13Rα2, CD44) and activating downstream signaling pathways (e.g., MAPK, PI3K/AKT)." (PMID 40260255, 2025). "This conclusion was supported by the finding that CHI3L1-driven metastasis was dramatically reduced in IL-13Rα2 KO mice, confirming that IL-13Rα2 is essential for CHI3L1-mediated tumor progression in this model." (PMID 40643503, 2025). "CHI3L1 is instrumental in tumor development, facilitating growth, invasion, and immune evasion through multiple mechanisms." (PMID 39827337, 2025). "These approaches will provide deeper insights into the specific roles of CHI3L1 in both tumor cells and the surrounding microenvironment." (PMID 40260255, 2025).
tumor (continued). "Another study reported that CHI3L1 mRNA expression increased with tumor progression in the AOM/DSS model, with particularly high levels in the distal colon." (PMID 40643503, 2025). "In frozen tissue samples, median CHI3L1 and osteopontin concentrations were around 100 and 10 times higher, respectively, in tumor samples than in controls." (PMID 40703808, 2025). "In contrast, activation of the RIG-I pathway can inhibit the expression of CHI3L1, which in turn downregulates molecules such as PD-L1, thereby enhancing anti-tumor immune responses." (PMID 40166469, 2025). "In the context of GC, CHI3L1 is upregulated and positively correlated with the depth of tumor invasion, lymph node status, and tumor staging." (PMID 40108688, 2025). "Porphyromonas gingivalis induces a protumor phenotype by impairing iNKT (invariant natural killer T) cell cytotoxicity through upregulation of chitinase-3-like-protein-1 (CHI3L1) and by promoting neutrophil recruitment within the tumor microenvironment." (PMID 41155306, 2025). "Murine models have proven to be particularly valuable tools for analyzing CHI3L1-mediated immunological effects, tissue remodeling, and tumor promotion." (PMID 40643503, 2025). "CHI3L1, mainly produced by infiltrating M2 macrophages in the tumor microenvironment, induced expression and secretion of growth differentiation factor 15 (GDF15) in tumor cells." (PMID 40313579, 2025). "CHI3L1 enhances tumor growth primarily by stimulating angiogenesis, the formation of new blood vessels, which supplies tumors with essential nutrients and oxygen." (PMID 39827337, 2025). "Transcriptomic profiling of tumor tissue revealed that elevated plasma CHI3L1 levels were positively correlated with aberrant PPAR signaling, peroxisomal function, and arachidonic-acid metabolism." (PMID 41568005, 2025). "CHI3L1 induces M2-type macrophages through the IL-13Rα2-mediated signaling cascade; in turn, these macrophages promote tumor cell proliferation, immunosuppression, and angiogenesis." (PMID 40643503, 2025). "CHI3L1 directly promotes tumor cell proliferation and angiogenesis and also contributes to immune evasion by establishing an immunosuppressive environment in inflamed tissues." (PMID 40643503, 2025). "Another study has indicated that CHI3L1 promotes the polarization of M2 macrophages, which contributes to immune evasion and tumor progression." (PMID 40692872, 2025). "In a mouse model of Lewis lung carcinoma, administration of an anti-CHI3L1 antibody significantly suppressed tumor growth and metastasis." (PMID 40643503, 2025). "For example, upregulation of genes (e.g. CHI3L1, S100A7, and MAL) is associated with poor prognosis, increases aggressiveness, and tumor microenvironment modulation." (PMID 40802546, 2025). "Evidence indicates that M2 macrophages enhance tumor aggressiveness through the secretion of chitinase-3 like protein 1 (CHI3L1)." (PMID 41409281, 2025). "CHI3L1 is primarily secreted by macrophages, fibroblasts, and tumor cells, and is involved in extracellular matrix remodeling, cell proliferation, angiogenesis, and regulation of inflammatory responses." (PMID 40260255, 2025). "Here, the antibody displayed a significant inhibitory effect on cell migration and tube formation of CHI3L1 expressing tumor cells." (PMID 40313579, 2025). "While the role of CHI3L1 suggested a previously unrecognized interaction between the tumor microenvironment and muscle metabolism." (PMID 41211064, 2025). "Understanding the role of CHI3L1 in shaping the tumor environment and promoting cancer growth is crucial, emphasizing its importance as a target for new treatments." (PMID 39827337, 2025).